PTBP1 (polypyrimidine tract binding protein 1)
Diseases named in the same sentence as PTBP1 in open-access papers (continued):
Sharing a sentence is not in itself a finding about the gene and the disease.
melanoma (10 papers, 2019 to 2025). A malignant, usually aggressive tumor composed of atypical, neoplastic melanocytes. "PTBP1 deficiency in dendritic cells can increase antitumor immunity and is also relevant to the CD44v6 variant expression in melanoma brain metastasis." (PMID 38462618, 2024). "However, the association between PTBP1 and circRNA in melanoma remains to be elucidated." (PMID 41347180, 2025). "Our findings suggest that the natural metabolite 6-MF can inhibit PTBP1 expression in melanoma cells in a dose- and time-dependent manner, thereby reducing circPIAS1 biogenesis and circPIAS1-108aa protein expression." (PMID 41347180, 2025). "PTBP1 is expressed by melanoma stem cells and it has been shown to regulate CD44v6 expression in melanoma brain metastases." (PMID 35269844, 2022). "The results showed that the depletion of PTBP1 significantly increased the proportion of cells in G0/G1 phase, indicating that the PTBP1 silencing led to the cell cycle arrest of melanoma stem cells." (PMID 33149126, 2020). "In patients with melanoma, the expressions of PTBP1 and LHFPL3-AS1 were significantly upregulated compared with the healthy donors." (PMID 33149126, 2020). "At the same time, the Kaplan–Meier survival analysis revealed that the melanoma patients with high PTBP1 expression level had distinct shorter survival rate compared with the patients with low PTBP1 level." (PMID 33149126, 2020). "Collectively, our findings indicated that PTBP1 was required for maintaining the stemness of melanoma stem cells." (PMID 33149126, 2020). "In order to characterize the role of PTBP1 in melanoma stem cells, melanoma stem cells stably overexpressing PTBP1-targeted shRNA were established using lentivirus transfection." (PMID 33149126, 2020). "At the same time, the PTBP1 silencing significantly decreased the percentage of tumorsphere formation of melanoma stem cells compared with the control." (PMID 33149126, 2020). "The PTBP1 silencing led to a significant decrease of the viability of melanoma stem cells compared with the control, suggesting that PTBP1 had a positive role on the proliferation of melanoma stem cells." (PMID 33149126, 2020). "In this study, our results indicated that the PTBP1 protein was responsible for the biogenesis of LHFPL3-AS1-long by promoting the splicing of LHFPL3-AS1 precursor in melanoma stem cells." (PMID 33149126, 2020). "In melanoma, PTBP1‐mediated splicing of the lncRNA LHFPL3‐AS1 precursor produces the lncRNA LHFPL3‐AS1‐long that inhibits the degradation of its target gene, Bcl‐2 mRNA, and upregulates the expression of Bcl‐2 by acting on miR‐181, which inhibits apoptosis and promotes melanoma stem cell death." (PMID 40579921, 2025). "In this context, our study revealed a mechanistic crosstalk among an onco-splicing factor, alternative splicing event of lncRNA and tumorigenesis of melanoma stem cells, enabling PTBP1 and the splicing of LHFPL3-AS1 to serve as the attractive therapeutic targets for melanoma." (PMID 33149126, 2020). "Quantitative real-time PCR showed that PTBP1 was knocked down in melanoma stem cells." (PMID 33149126, 2020). "Quantitative real-time PCR results showed that the PTBP1 silencing led to significant downregulations of stemness genes (Klf4, Nanog, Oct4, and Sox2) compared with the controls, indicating that PTBP1 played a positive role in maintaining the stemness of melanoma stem cells." (PMID 33149126, 2020). "In melanoma stem cells, the alternative splicing of the LHFPL3-AS1 transcript was controlled by the splicing factor polypyrimidine tract binding protein 1 (PTBP1)." (PMID 39170516, 2024). "In primary melanoma, a close correlation exists between splicing factors, such as ESRP1, ESRP2, PTBP1, and U2 snRNP auxiliary factor (U2AF2), and the expression of CD44v6." (PMID 38462618, 2024).
melanoma (continued). "Specific deletion of PTBP1 in the hnRNP family in melanoma enhances MHC II expression and disrupts T-cell homeostasis, and hnRNP A1 assists in T-lymphocyte recognition in melanoma cells." (PMID 38462618, 2024). "Evaluation of the predictive power of this novel signature in silico on an ICI-treated melanoma patient cohort extracted from GEO and EGA databases, revealed WFDC1, EFNA3, DDX10, and PTBP1 as marker genes." (PMID 35269844, 2022). "6-MF targets PTBP1 to inhibit circPIAS1 biogenesis and reduce circPIAS1-108aa.6-MF inhibits PI3K-AKT pathway; combined with IFN-γ, it enhances STAT1 phosphorylation, inhibits SLC7A11/GPX4 pathway, promoting melanoma ferroptosis." (PMID 41347180, 2025). "Expressions of PTBP1 and LHFPL3-AS1 were considerably increased in melanoma patients." (PMID 39170516, 2024). "In this study, our findings revealed that the lncRNA LHFPL3-AS1-long, generated from the polypyrimidine tract binding protein 1 (PTBP1)-mediated splicing of the LHFPL3-AS1 precursor, upregulated BCL2 protein to contribute to tumorigenesis of melanoma stem cells." (PMID 33149126, 2020). "Therefore, our study revealed a mechanistic crosstalk among an onco-splicing factor, lncRNA and tumorigenesis of melanoma stem cells, enabling PTBP1 and LHFPL3-AS1 to serve as the attractive therapeutic targets for melanoma." (PMID 33149126, 2020).
osteosarcoma (10 papers, 2020 to 2025). A usually aggressive malignant bone-forming mesenchymal neoplasm, predominantly affecting adolescents and young adults. "Altogether, the key findings of the present study highlight ELK1/miR-134/PTBP1 signaling cascade as a novel molecular mechanism underlying the acquisition of osteosarcoma chemoresistance." (PMID 33621196, 2021). "Together, these results suggest that PTBP1 up‐regulation is associated with the cisplatin resistance of osteosarcoma at the cellular level." (PMID 32207235, 2020). "Aberrant expression of PTBP1 has been observed in osteosarcoma tissues, and it is associated with poor response to chemotherapy." (PMID 32207235, 2020). "Currently, the status of PTBP1 in osteosarcoma and the underlying regulatory mechanisms of PTBP1 affect biological characteristics, especially the chemotherapeutic response of osteosarcoma cells, and have not been clearly reported." (PMID 32207235, 2020). "However, the role of PTBP1 in osteosarcoma, especially in chemoresistant osteosarcoma, and the underlying mechanism remain unclear." (PMID 32207235, 2020). "An analysis performed on a Cancer Genome Atlas (TCGA) data set demonstrated an upregulation of CTR1 in response to RNA-binding protein (PTBP1) inhibition, enhancing osteosarcoma cells’ chemosensitivity to cisplatin." (PMID 40282556, 2025). "Collectively, our findings demonstrated that ELK1 functioned as a facilitator of chemoresistance in osteosarcoma cells by increasing cell viability and proliferation via miR-134 inhibition and upregulation of PTBP1." (PMID 33621196, 2021). "Initially, the data obtained during the present study demonstrated that ELK1 and PTBP1 were highly expressed while miR-134 was poorly expressed in osteosarcoma tissues and cell lines." (PMID 33621196, 2021). "PTBP1 enhanced chemoresistance in cultured osteosarcoma cells in vitro and in vivo by increasing aerobic glycolysis." (PMID 33621196, 2021). "Kaplan-Meier survival analysis demonstrated that patients with higher PTBP1 expression in osteosarcoma tissues had poor overall survival and disease-free survival." (PMID 33621196, 2021). "Future studies are required to fully clarify the specific mechanisms by which ELK1 combined with miR-134 and PTBP1 influence chemoresistance to DXR treatment in osteosarcoma." (PMID 33621196, 2021). "The results showed that PTBP1 expression in osteosarcoma cell lines was higher than that in hFOB, and it significantly increased in DXR-resistant osteosarcoma cell lines (p < 0.05)." (PMID 33621196, 2021). "Next, we set out to further ascertain the role of PTBP1 in enhancing DXR resistant osteosarcoma cells in vivo." (PMID 33621196, 2021). "In the present study, we aim to investigate the role of PTBP1 in cisplatin‐resistant osteosarcoma; moreover, we sought to address the detail mechanisms on how PTBP1 affects the cisplatin resistance of osteosarcoma." (PMID 32207235, 2020). "As expect, these data suggest that SLC31A1 mediates the effect of PTBP1 knock‐down on the chemosensitivity of CISR osteosarcoma cells by regulating the uptake of cisplatin." (PMID 32207235, 2020). "Then, we demonstrated that PTBP1 knock‐down enhanced the chemosensitivity of cisplatin‐resistant osteosarcoma cells to cisplatin by directly up‐regulating the expression level of SLC31A1." (PMID 32207235, 2020). "Collectively, the present study suggests that PTBP1 is a crucial determinant of chemoresistance in osteosarcoma." (PMID 32207235, 2020). "To further investigate the role of PTBP1 in CISR osteosarcoma cells, we silenced PTBP1 expression in MG‐63CISR and U‐2OSCISR cells using shRNA specific for PTBP1." (PMID 32207235, 2020). "Then, we conducted in vitro assays and in vivo experiments, and the results demonstrated that knock‐down PTBP1 in CISR osteosarcoma cells enhances the anti‐tumour effect of cisplatin." (PMID 32207235, 2020).
osteosarcoma (continued). "The results implied that PTBP1 knock‐down in cisplatin‐sensitive osteosarcoma cells also increased the expression of SLC31A1." (PMID 32207235, 2020). "We found that PTBP1 was significantly increased in chemotherapeutically insensitive osteosarcoma tissues and cisplatin‐resistant osteosarcoma cell lines (MG‐63CISR and U‐2OSCISR) as compared to chemotherapy‐sensitive osteosarcoma tissues and cell lines." (PMID 32207235, 2020). "We first confirmed that PTBP1 expression was increased in human osteosarcoma tissues, especially tissues with a poor response to chemotherapy." (PMID 32207235, 2020). "In conclusion, our study reveals the role of PTBP1 in CISR osteosarcoma cells and its relevance with prognosis of osteosarcoma patients." (PMID 32207235, 2020). "Taken together, these results demonstrate that PTBP1 up‐regulation is associated with poor response to chemotherapy of osteosarcoma, and higher PTBP1 expression predicts worse prognoses in osteosarcoma patients." (PMID 32207235, 2020). "Real‐time quantitative PCR and Western blot analysis showed that the expression of PTBP1 in the osteosarcoma cell lines MG‐63 and U‐2OS was higher than that in the human osteoblast cell line NHOst." (PMID 32207235, 2020). "To further investigate the effect of PTBP1 knock‐down in vivo, we carried out osteosarcoma xenograft and treatment experiments in nude mice." (PMID 32207235, 2020). "On this basis, we revealed that PTBP1 is aberrantly expressed in osteosarcoma tissues and cells, especially those insensitive to chemotherapeutics." (PMID 32207235, 2020). "The PTBP1 expression level was higher in 19 osteosarcoma tissues than that in the matched normal tissues." (PMID 32207235, 2020). "Together, PTBP1 knock‐down potentiates the anti‐tumour effect of cisplatin on cisplatin‐resistant osteosarcoma in vivo." (PMID 32207235, 2020). "Using a nude mouse xenograft model, we further confirmed that PTBP1 knock‐down enhanced chemoresistant osteosarcoma responsiveness to cisplatin treatment in vivo." (PMID 32207235, 2020). "Haiyi Gong found that the knockout of the expression of PTBP1 could reduce cell proliferation, migration, and invasion, and significantly affect the cell cycle in osteosarcoma tumors." (PMID 38247832, 2024). "Moreover, recent studies demonstrated the miR-134/PTBP1 signaling cascade was involved in aerobic glycolysis to enhance osteosarcoma chemoresistance, indicating PTBP1 plays important regulatory roles in glucose metabolism." (PMID 36447254, 2022). "Next, to investigate the relationship between PTBP1 and drug-resistant osteosarcoma cells, we determined the expression of PTBP1 in human osteoblast line (hFOB), DXR-resistant osteosarcoma cell lines (U2OS/DXR, MG63/DXR, HOS/DXR) and their parental cells by RT-qPCR." (PMID 33621196, 2021). "Thus, the current study aimed to elucidate the role of ELK1/miR-134/PTBP1 signaling cascade in osteosarcoma chemoresistance." (PMID 33621196, 2021). "Thus, our study set out to investigate the role of ELK1 regulating miR-134 and PTBP1 in chemoresistance to osteosarcoma cells." (PMID 33621196, 2021). "Overall, these results reveal that inhibiting PTBP1 expression could enhance the killing effect of cisplatin on CISR osteosarcoma cells." (PMID 32207235, 2020). "Consequently, from the perspective of post‐transcriptional regulation, we identified SLC31A1 as the target of PTBP1 in CISR osteosarcoma cells by transcriptome sequencing, RIP assay and luciferase reporter assay." (PMID 32207235, 2020). "In this study, we aimed to explore the functions of PTBP1 in chemoresistance of osteosarcoma." (PMID 32207235, 2020). "Moreover, immunohistochemistry (IHC) staining indicated that PTBP1 knock‐down combined with cisplatin treatment produced a significant pro‐apoptotic effect in osteosarcoma in vivo." (PMID 32207235, 2020).
osteosarcoma (continued). "Moreover, we processed the clinical data of all patients to explore the relationship between PTBP1 expression and the clinical and pathological characteristics in 25 osteosarcoma patients." (PMID 32207235, 2020). "Because PTBP1 expression exhibits an increasing tendency in some common cancers, we investigated whether PTBP1 has a role in osteosarcoma, especially in the chemoresistance of osteosarcoma." (PMID 32207235, 2020). "In osteosarcoma cells, the ELK1/miR‐134/PTBP1 axis of action promotes resistance to adriamycin in osteosarcoma cells." (PMID 40579921, 2025). "In conclusion, the central findings of the current study present evidence indicating that ELK1 promotes the chemoresistance of osteosarcoma cells to DXR via downregulation of miR-134 and upregulation of PTBP1." (PMID 33621196, 2021). "Taken together, significant evidence exists suggesting that ELK1 is able to promote the chemoresistance of osteosarcoma cells to DXR by promoting aerobic glycolysis and cell viability of osteosarcoma cells via upregulation of miR-134-targeted PTBP1." (PMID 33621196, 2021). "A notable finding in the present study revealed that ELK1 promoted chemoresistance of osteosarcoma cells to DXR by enhancing aerobic glycolysis and cell viability via inhibition of miR-134 and upregulation of PTBP1." (PMID 33621196, 2021). "In this study, we demonstrated the biological roles of PTBP1 and SLC31A1 in chemoresistant osteosarcoma for the first time." (PMID 32207235, 2020). "Western blot analysis revealed an increased expression of PTBP1 in parental U2OS, MG63, and HOS cells in the presence of PTBP1, and decreased PTBP1 expression in DXR-resistant osteosarcoma cells in the absence of PTBP1 (p < 0.05)." (PMID 33621196, 2021). "PTBP1 affects the expression level of SLC31A1 by binding to its mRNA, thereby affecting the uptake of cisplatin by CISR osteosarcoma cells and regulating the sensitivity of CISR osteosarcoma cells to cisplatin." (PMID 32207235, 2020). "Together, these results suggest that the expression of SLC31A1 is decreased in chemotherapy‐insensitive osteosarcoma tissues and CISR osteosarcoma cells, and the effect of PTBP1 knock‐down on SLC31A1 up‐regulation is not unique to CISR cells." (PMID 32207235, 2020). "Furthermore, we validated the regulatory effect of PTBP1 on the expression of SLC31A1 and chemosensitivity enhanced by PTBP1 knock‐down is mediated by SLC31A1 in CISR osteosarcoma cells through a series of assays." (PMID 32207235, 2020). "Next, we examined the level of PTBP1 in osteosarcoma cells and CISR osteosarcoma cells." (PMID 32207235, 2020). "In addition, we identified that siRNA-mediated knockdown of GLUT3 along with overexpressed PTBP1 reversed the effects of overexpressed PTBP1 in U2OS/DXR cells, suggesting that PTBP1 or GLUT3 facilitated chemoresistance of osteosarcoma cells to DXR by enhancing aerobic glycolysis." (PMID 33621196, 2021). "Differential analysis of the osteosarcoma-related microarray data GSE12805 containing tumor tissues (n = 40) and normal tissues (n = 13) was performed using R language with |log2FC|> 1 and p-value < 0.05 as threshold, with results indicating that PTBP1 was upregulated in osteosarcoma." (PMID 33621196, 2021). "The results of qRT‐PCR analysis showed that the expression of SLC31A1 mRNA was down‐regulated in osteosarcoma tissues, especially lower in chemotherapy‐insensitive osteosarcoma tissues, and there was a negative correlation between the expression of SLC31A1 and PTBP1 in osteosarcoma tissue." (PMID 32207235, 2020). "EdU assay revealed that cell proliferation was promoted in the parental U2OS, MG63, and HOS cells in the presence of PTBP1, and was inhibited in DXR-resistant osteosarcoma cells in the absence of PTBP1 (p < 0.05)." (PMID 33621196, 2021).
osteosarcoma (continued). "The results revealed enhanced cell viability and increased IC50 in parental U2OS, MG63, and HOS cells in the presence of PTBP1, while a contrasting trend was identified in the DXR-resistant osteosarcoma cells in the absence of PTBP1 (p < 0.05)." (PMID 33621196, 2021).
cervical carcinoma (9 papers, 2018 to 2025). A carcinoma arising from either the exocervical squamous epithelium or the endocervical glandular epithelium. "Considering that SFTA1P and PTBP1 have the same tumor-promoting roles in cervical cancer, we focused on genes that were simultaneously up- or down-regulated in SFTA1P knockdown and PTBP knockdown cancer cells." (PMID 36344495, 2022). "Analysis of its mechanism revealed that lncRNA SFTA1P regulates cervical cancer progression by interacting with PTBP1 protein to facilitate TPM4 decay." (PMID 36344495, 2022). "Furthermore, through interactions with recombinant Polypyrimidine Tract Binding Protein 1 (PTBP1), LncRNA surfactant associated 1 (SFTA1P) promoted the degradation of tropomyosin 4 (TPM4) mRNA and the progression of cervical cancer." (PMID 37007117, 2023). "Similarly, we also explored the role of PTBP1 in regulating the function of TPM4 in cervical cancer." (PMID 36344495, 2022). "However, the biological functions of PTBP1 in cervical cancer remains to be explored." (PMID 36344495, 2022). "For instance, Aoran Luo demonstrated that PTBP1 interacted with lncRNA SFTA1P to regulate the degradation of TPM4 mRNA, thereby promoting the proliferation, migration, and invasion of cervical cancer cells." (PMID 38247832, 2024). "Multiple hnRNPs, including hnRNP A1/A2, hnRNP C1/C2, hnRNP H, and hnRNP I (also referred to as polypyrimidine tract-binding protein 1, PTBP1), are significantly upregulated in HPV-induced high-grade lesions and cervical cancer tissues." (PMID 35563334, 2022). "Human myoblasts showed higher levels of PTBP1 than the mouse muscle, while the muscle cancer cell line RD4 and the cervical cancer cell line HeLa showed significantly higher levels of PTBP1." (PMID 30209894, 2018).
diabetes (9 papers, 2010 to 2025). "PTBP1 plays a pivotal role in the mRNA stabilization and translation of insulin in the pancreas and it has been associated with diabetes." (PMID 26566043, 2015). "This PTBP1 spliced variant induced by diabetes has a lower inhibitory splicing activity." (PMID 36277184, 2022). "Polypyrimidine tract-binding protein 1 (PTBP1), CUGBP Elav-like family member (CELF) and RBFOX2 are associated with aberrant alternative splicing in diabetes." (PMID 35597446, 2022). "More specifically, the second stage of the multi-purpose allele after recombinase conversion could be used for the conditional knockout of PTBP1 in pancreatic β-cells only in order to test the role of this gene in insulin granule biogenesis and diabetes." (PMID 21423341, 2011). "Interestingly, our new analysis procedure subsequently identified CDC42 and PTBP1 as being equally targeted by both up- and down-regulated miRNAs; thus, CDC42 and PTBP1 should not be altered in vivo by diabetes (as we demonstrated by western blotting prior to developing our ranking metric)." (PMID 20353613, 2010).